RWDD3 (RWD domain containing 3)
Description:
Enhancer of SUMO conjugation. Via its interaction with UBE2I/UBC9, increases SUMO conjugation to proteins by promoting the binding of E1 and E2 enzymes, thioester linkage between SUMO and UBE2I/UBC9 and transfer of SUMO to specific target proteins which include HIF1A, PIAS, NFKBIA, NR3C1 and TOP1. Isoform 1 and isoform 2 positively regulate the NF-kappa-B signaling pathway by enhancing the sumoylation of NF-kappa-B inhibitor alpha (NFKBIA), promoting its stabilization which consequently leads to an increased inhibition of NF-kappa-B transcriptional activity. Isoform 1 and isoform 2 negatively regulate the hypoxia-inducible factor-1 alpha (HIF1A) signaling pathway by increasing the sumoylation of HIF1A, promoting its stabilization, transcriptional activity and the expression of its target gene VEGFA during hypoxia. Isoform 2 promotes the sumoylation and transcriptional activity of the glucocorticoid receptor NR3C1 and enhances the interaction of SUMO1 and NR3C1 with UBE2I/UBC9. Has no effect on ubiquitination.
Synonyms: RSUME; DKFZP566K023
Tractability: PROTAC: ubiquitination databases record sites on it.
Gene: Protein-coding gene on chromosome 1 (95,234,189 to 95,247,685, forward strand). Ensembl gene ENSG00000122481.
Subcellular location: Nucleus; Cytoplasm
Pathways (Reactome):
Metabolism of proteins: SUMO is transferred from E1 to E2 (UBE2I, UBC9)
Gene Ontology:
Molecular function: protein binding
Biological process: positive regulation of hypoxia-inducible factor-1alpha signaling pathway; positive regulation of protein sumoylation
Cellular component: cytoplasm; nucleus
Genetic constraint (gnomAD): Loss-of-function variants: 19 observed, 17.29 expected, observed/expected ratio (o/e) 1.1, 90% interval 0.77 to 1.61. The upper end of that interval is the gene's LOEUF score, 1.61, which puts it in group 6 of 6, group 1 being the genes least tolerant of losing a copy. Missense variants: 220 observed, 229.74 expected, observed/expected ratio (o/e) 0.96, 90% interval 0.86 to 1.07. Synonymous variants: 83 observed, 86.36 expected, observed/expected ratio (o/e) 0.96, 90% interval 0.8 to 1.15.
Homologues: Orthologues: chimpanzee RWDD3 (98% identical), macaque TLCD4 (95% identical), dog RWDD3 (88% identical), pig RWDD3 (83% identical), rat Rwdd3 (80% identical), mouse Rwdd3 (79% identical), rabbit RWDD3 (78% identical), tropical clawed frog rwdd3 (56% identical), guinea pig RWDD3 (56% identical).
Diseases named in the same sentence as RWDD3 in open-access papers:
RWDD3 is named in the same sentence as 5 diseases in open-access papers, as found by Europe PMC text mining. Sharing a sentence is not in itself a finding about the gene and the disease.
RWDD3 shares sentences with these, for which no sentence is quoted: cancer (2 papers); breast carcinoma (1); clear cell renal cell carcinomas (1); lung adenocarcinoma (1); neuropathy (1).